EPO (erythropoietin)
Diseases named in the same sentence as EPO in open-access papers (continued):
Sharing a sentence is not in itself a finding about the gene and the disease.
anemia (continued). "In mice, deletion of EPO (Epo−/−) or EpoR (EpoR−/−) leads to angiogenic defects detectable at day E10.5, two days prior to the onset of severe anemia." (PMID 22567318, 2012). "In this study, EPO administration either orally or subcutaneously prevented prematurity anemia in the 4th week, but better results were obtained in the subcutaneous EPO group." (PMID 22737576, 2012). "Iron deficiency is recognised as a significant factor affecting ESA response, and is usually treated alongside erythropoietin replacement as part of co-ordinated anaemia management in the CKD population." (PMID 22768256, 2012). "It has been reported that EPO improves anaemia induced by imatinib therapy in patients with chronic myeloid leukaemia in chronic phase." (PMID 22950685, 2012). "Recent studies indicate an increase in tumor progression and recurrence in head and neck squamous cell carcinomas (HNSCC) of cancer patients taking recombinant human erythropoietin (rhEpo) for anemia." (PMID 22188703, 2011). "Understanding the nature of renal erythropoietin-producing cells (REPs) remains a central challenge for elucidating the mechanisms involved in hypoxia and/or anemia-induced erythropoietin (Epo) production in adult mammals." (PMID 22022454, 2011). "A second way is to supplement combination therapy with growth hormones, such as erythropoietin, that increase the production of red blood cells (erythrocytes) and compensate for ribavirin-induced anemia." (PMID 21304937, 2011). "Recombinant human erythropoietin (rHU EPO) has been available for the treatment of anemia of CKD since the 1980s and supplanted the use of blood transfusions and adrogenic steroids." (PMID 21541213, 2011). "Perhaps more studies can address utilization of ferritin as a possible marker for EPO activity in addition to measuring the response to anemia in this cohort of patients." (PMID 21713081, 2011). "There is still a need for properly designed clinical trials to assess the efficacy of EPO beyond anemia." (PMID 21943500, 2011). "Another and more effective alternative for the correction of preoperative anemia is the administration of recombinant human erythropoietin (rHuEPO)." (PMID 22051161, 2011). "Secretion of EPO from the kidney is required for regulation of erythropoeisis and to avoid severe anemia secondary to CKD." (PMID 21957910, 2011). "Other mechanisms for anemia include an inflammatory response with blunted erythropoietin (EPO) production, abnormalities in iron metabolism, and altered proliferation and differentiation of medullar erythroid precursors." (PMID 21970512, 2011). "Recombinant human EPO (rHuEPO) is commercially available and is widely used for the treatment of anemia." (PMID 21906325, 2011). "In consequence, the visible pattern of EPO distribution among the study groups should vary according to the degree of anemia." (PMID 21912616, 2011). "Availability of recombinant EPO has eliminated the need for blood transfusion and now it is extensively used for the treatment of anemia." (PMID 22040235, 2011). "One well-established modified EPO, darbepoetin alfa (Aranesp, NESP), is a heavily glycosylated EPO analogue that has been used for 10 years to treat anemia." (PMID 21957455, 2011). "43.9% of this study population didn't receive EPO during dialysis because of financial reasons which reflects poor management of anaemia among our patients in the pre-transplant period." (PMID 21827693, 2011). "Ribavirin was reduced transiently in two patients because of anemia and both patients received erythropoietin a at a dose of four thousand units twice a week for a month." (PMID 21372348, 2011). "In summary, an adequate EPO and ferritin response to anemia in patients with lymphoma was demonstrated in our study." (PMID 21713081, 2011). "Anemia in patients with chronic kidney disease is due to a number of factors, the most common of which is abnormally low erythropoietin levels." (PMID 21869890, 2011).
anemia (continued). "In agreement with that, the highest levels of bilirubin and LDH (both indicators of hemolysis) concentrated in the SM group, coinciding with the highest ratios of severe anemia and EPO levels among the study children." (PMID 21912616, 2011). "Not only has erythropoietin (EPO) therapy been reported to enhance erythropoiesis in the treatment of anemia, but it has also been shown to alleviate ischemia-related organ dysfunction through anti-ischemic and cellular protective effects." (PMID 21864394, 2011). "Nine of 10 patients achieved an SVR, but the side effects, in particular anemia that required erythropoietin, were much more frequent and severe." (PMID 22087150, 2011). "We observed higher ferritin levels in lymphoma patients with high EPO levels compared to healthy controls (P<0.001), that has been explained by erythropoietic response to anemia." (PMID 21713081, 2011). "Erythropoietin is a growth factor commonly used to manage anemia in patients with chronic kidney disease." (PMID 20169072, 2010). "Management of anemia with erythropoietin in patients with renal failure on dialysis has significantly changed clinical practice in nephrology." (PMID 20169072, 2010). "This suggests that anemia is the result of an immune response that neutralized with activity of both the rhuEPO and the mouse erythropoietin for an extended period." (PMID 21203556, 2010). "Although many reports have noted the synergy between EPO and G-CSF in the treatment of anemia in myelodysplastic syndromes (MDS), investigators did not propose any mechanism to explain the results of clinical trial." (PMID 20404921, 2010). "Reduced tissue oxygen levels, as observed in anaemia, induce upregulation of EPO by HIF1A and a subsequent rise in RBC production." (PMID 20844758, 2010). "Anemia management was revolutionized after the advent of recombinant human erythropoietin and later parenteral iron therapy." (PMID 21072151, 2010). "In chronic disease states, inflammatory cytokines are thought to contribute to the development of anemia by shortening red blood cell survival and impairing ability of red blood cell progenitors to respond to erythropoietin." (PMID 20233445, 2010). "In most cases of anemia, the imbalance is magnified by tissue hypoxia with increased erythropoietin production." (PMID 20467559, 2010). "Nevertheless, EPO has been safely used in humans for many years for treating anemia, and in trials that tested EPO as a neuroprotective/neuroregenerative agent." (PMID 21085572, 2010). "Nevertheless, erythropoietin therapy still remains a cornerstone in the management of anemia in chronic dialysis patients." (PMID 20169072, 2010). "Because of its stimulating effect on RBC production, erythropoietin (Epo) is used to treat anemia, for example, in patients on dialysis or on chemotherapy." (PMID 21490911, 2010). "Anemia is common among individuals with reduced kidney function, generally because of a decreased production of erythropoietin." (PMID 20950484, 2010). "The role of erythropoietin in patients with normocytic, normochromic anaemia in HF is being evaluated." (PMID 21150007, 2010). "Recombinant human erythropoietin (r-HuEPO) is used to treat symptomatic anaemia due to chemotherapy." (PMID 21331363, 2010). "Both its basal activity under physiological conditions and its increased activity under anemia-induced stress conditions are highly stimulated by the hormone erythropoietin." (PMID 20711497, 2010). "Androgens have been shown to increase erythropoietin levels and hematopoietic stem cell cycling; however it seems more likely that an unrelated mechanism led to improvement in the anemia and iron homeostasis in these cases." (PMID 20368776, 2010). "Recombinant human erythropoietin has been used in the treatment of anaemia due to chemotherapy for more than 20 years." (PMID 21331363, 2010). "The primary stimulus for EPO release is decreased oxygen delivery, most often due to anemia or hypoxia." (PMID 19930719, 2009).
anemia (continued). "The lack of evidence for a response by Ptp4a1 and Tnfrs11a to infection is consistent with previous reports of a blunted response to erythropoietin in the anaemia of chronic disease." (PMID 19365556, 2009). "It has been reported that matrix-embedded MSCs, genetically modified to produce erythropoietin (EPO) and subcutaneously inoculated in a mouse model of anemia, supported the release of the protein into the bloodstream for a sustained pharmacological effect." (PMID 19096041, 2009). "Most physicians prescribe EPO for patients with anemia who had a prior diagnosis of chronic kidney injury rather than for those with ARF." (PMID 19166584, 2009). "Millions of patients have already been receiving EPO as a highly efficacious and safe treatment for anemia." (PMID 20142991, 2009). "In substitution to blood transfusion as anti-anemia therapy, some erythroid stimulating agents have been developed including human recombinant erythropoietin (hrEpo)." (PMID 20204172, 2009). "Accordingly, both hypoxia and anemia induce the synthesis of erythropoietin (EPO) and are the two main signals that increase iron absorption independently of iron stores." (PMID 21415988, 2009). "We report on long-term survival of these patients in relation to anemia and its management with EPO and IV iron." (PMID 19245700, 2009). "At that time, her hemoglobin was 6 g/dL, and her anemia was unresponsive to erythropoietin treatment." (PMID 19936245, 2009). "Subcutaneous injections of erythropoietin and granulocyte-colony stimulating factor (G-CSF) were used in 7 patients (19.4% of patients who developed anemia) and 10 patients (25.6% of patients who developed leukopenia), respectively." (PMID 19139619, 2009). "Intravenous administration of EPO to treat azotemia-induced anemia in diabetic patients demonstrated a beneficial effect on macular edema and improved visual outcome." (PMID 19930719, 2009). "We also provide evidence of large diurnal oscillations in serum erythropoietin levels during anaemia." (PMID 19557192, 2009). "Erythropoietin (EPO), a 165 amino acid glycoprotein cytokine, has been used extensively for the treatment of anemia in humans and has been shown to have the capacity to induce neuroprotection in a disparate variety of animal models of nervous system disease." (PMID 18382691, 2008). "It is difficult to compare EPO doses between studies focussing on anaemia management, because in ESAM 2003 and DOPPS II, EPO doses were not normalized to body weight." (PMID 19077225, 2008). "The first randomized trial in cancer patients demonstrated that recombinant human erythropoietin is effective for treating anemia in cancer patients on chemotherapy." (PMID 18231643, 2008). "Events occurring in a notably greater proportion of erythropoietin-treated patients than erythropoietin-naïve patients were fatigue (47% vs. 33%), anaemia (16% vs. 7%) and upper respiratory tract infection (15% vs. 4%)." (PMID 18540943, 2008). "This anemia can be corrected with exogenous erythropoietin growth factors, of which three available are worldwide: epoetin alfa, epoetin beta, and darbepoetin alfa." (PMID 18231643, 2008). "Because its primary amino acid sequence is unrelated to that of rhEPO, Hematide is unlikely to induce a cross-reactive immune response against endogenous EPO and is reported to correct anaemia induced by anti-rhEPO antibodies in a rat PRCA model." (PMID 18510682, 2008). "The two most important initial steps in the management of anti-EPO antibody-mediated PRCA are transfusions for symptomatic anaemia and stopping the administration of rhEPO." (PMID 18510682, 2008). "Erythropoietin (Epo) was first identified as an haematopoietic growth factor produced in the kidneys, and recombinant human Epo (rhEpo) is widely used to treat anaemia." (PMID 18179698, 2008). "Recombinant human erythropoietin was first used clinically in renal dialysis patients in the 1980s, at which time it was shown to correct anemia in end-stage renal disease." (PMID 18231643, 2008).
anemia (continued). "The correction of anemia (e.g. by erythropoietin) reduces the oxidative stress to some extent, and also the cardiovascular risk." (PMID 19578522, 2008). "Recent clinical studies have shown that administration of recombinant human erythropoietin (rhEPO, epoetin alfa) increases haemoglobin levels and improves quality of life in patients with cancer-related anaemia." (PMID 17299396, 2007). "Examples of interesting pre-clinical experiments with gene transfer to muscle tissue include correction of anaemia or β-thalassemia by electrotransfer of EPO." (PMID 17598924, 2007). "With impaired production and/or activity of erythropoietin, the anemia is usually hypoproliferative, as determined by the absolute reticulocyte count." (PMID 17910755, 2007). "In head and neck cancer patients undergoing RT and randomised to therapy with epoetin beta or placebo, locoregional control and survival were significantly worse in the EPO-treated group, although anemia was corrected in these patients." (PMID 17299396, 2007). "The purpose of this study was to evaluate the impact of recombinant human erythropoietin (rHuEPO) use for anemia of critical illness at a practice site where delayed initiation is common." (PMID 17916251, 2007). "Owing to the frequently reported anaemia in the feasibility and efficacy study, erythropoietin was included in the trial as additional haematological support." (PMID 16909132, 2006). "Our findings that the EPO response to anemia was blunted in HIV-infected babies at 6 weeks and slightly attenuated at 3 months of age are consistent with several reports of studies carried out in HIV-infected adults." (PMID 16390553, 2006). "Among HIV-infected infants, the EPO response to anemia is attenuated near the time of infection in the first weeks of life, but normalizes by 6 months." (PMID 16390553, 2006). "The EPO response to anemia among HIV-infected infants was attenuated during early infancy but normalized at 6 months of age." (PMID 16390553, 2006). "Anemia is a frequent complication of chronic kidney disease, primarily due to failure of erythropoietin production to respond to decreased haemoglobin concentration." (PMID 16515712, 2006). "Among Pp infants, the EPO response to anemia was attenuated at 6 weeks and 3 months, but significant at 6 months." (PMID 16390553, 2006). "Among Nn babies, the EPO response to anemia became weaker with age, while among Pn and Pp babies, the response was stronger at 6 months than at 6 weeks or 3 months." (PMID 16390553, 2006). "Krafte-Jacobs and coworkers demonstrated a blunted EPO response in critically ill pediatric patients with acute anemia and acute hypoxia." (PMID 15987387, 2005). "We also include an illustrative example of the potential value of our method using reports from the Cochrane review on the role of erythropoietin in anemia due to malignancy." (PMID 15840177, 2005). "Recent evidence has demonstrated a blunted erythropoietin (EPO) response to be a factor contributing to anemia of critical illness in specific subsets of patients, including those with sepsis, multiple trauma, and pediatric critical illness." (PMID 15987387, 2005). "The aim of this study was to compare the pharmacokinetic, pharmacodynamic and safety properties of two recombinant EPO formulations in patients with anemia due to end-stage renal disease on hemodialysis." (PMID 15910687, 2005). "The authors concluded that the EPO response to anemia is severely blunted in critically ill patients." (PMID 15987387, 2005). "Recent evidence has demonstrated a blunted EPO response as a factor contributing to anemia of critical illness in specific subsets of patients." (PMID 15987387, 2005). "We evaluated the relationship of the endogenous EPO response to anemia in the setting of mechanical ventilation and demonstrated a significantly diminished response in this population." (PMID 15987387, 2005).
anemia (continued). "Because the premature infant has a diminished erythropoietin (EPO) response to anemia, the administration of exogenous recombinant EPO has been proposed as a promising therapy." (PMID 16080798, 2005). "Compared to patients without cancer who have iron-deficiency anaemia, anaemic cancer patients have a smaller increase in erythropoietin for their level of anaemia." (PMID 12799626, 2003). "Erythropoietin (epoietin) offers the chance to effectively ameliorate anaemia in cancer patients receiving chemotherapy." (PMID 14647149, 2003). "As would be expected in anaemia of chronic disease, laboratory indices indicated suppression of endogenous EPO and evidence of impaired iron utilisation." (PMID 12799626, 2003). "The prophylactic application of recombinant human erythropoietin (rHu-EPO) is capable of preventing anaemia and to decrease the frequency of transfusions in patients receiving cisplatin-based and non-platinum containing chemotherapy in several clinical trials." (PMID 12402143, 2002). "Recombinant human erythropoietin (rHuEPO) is effective for treating anaemia in patients receiving chemotherapy." (PMID 12177793, 2002). "Recombinant human erythropoietin (rHuEPO) has been advocated for the treatment of anaemia in patients submitted to cancer chemotherapy." (PMID 9743301, 1998). "In conclusion subcutaneous low dose of erythropoietin seems to be effective and safe in the treatment of cisplatin-induced anaemia." (PMID 8427776, 1993). "Recombinant human erythropoietin (EPO) is widely used to treat anemia." (PMID 41650961, 2026). "The present analyses, however, show that vadadustat provides regulated, limited inductions of endogenous EPO, improves iron availability, and represents a safe, effective alternative to the current treatment of patients with anemia and DD‐CKD, including patients requiring high ESA doses." (PMID 41376433, 2026). "According to the results of this study, it is suggested that PLR ≥ 143.4 (according to the best cutoff value of ROC) should be used as the screening threshold of anemia risk in MHD patients, and Hb should be monitored first in patients with high PLR and EPO dosage should be optimized." (PMID 41517734, 2026). "Normocytic normochromic anemia is characteristically related to chronic inflammatory states, where cytokine‐triggered retardation of erythropoietin release and iron‐restricted erythropoiesis lead to reduced erythrocyte production but do not affect red cell sizes and hemoglobinization." (PMID 41527292, 2026). "Further, pre-operative anemia management involving the assessment of iron levels or supplementation with erythropoietin therapy may be of substantial benefit." (PMID 39941664, 2025). "We propose that this phenomenon may be attributed to the fact that EPO production in sepsis is influenced not only by oxygen levels and renal function but also by inflammation and anemia, both of which are potent stimulators of EPO synthesis." (PMID 40114237, 2025). "The greater Hb rise in HF patients may be linked to improved oxygenation due to reduced fluid overload, while the lower increase in CKD patients could reflect baseline anemia or impaired erythropoietin production." (PMID 40640769, 2025). "These hematological abnormalities may reflect physiological challenges in preterm infants, such as impaired kidney function and reduced EPO production, contributing to anemia in early life." (PMID 39940677, 2025). "In parallel, hypoxia-inducible factor (HIF) prolyl-hydroxylase inhibitors, such as daprodustat and vadadustat, correct CKD-related anemia by stabilizing HIF-α, thereby increasing endogenous erythropoietin and lowering hepcidin to improve functional iron deficiency." (PMID 41367439, 2025). "EPO hyporesponsiveness may complicate the management of anemia in these patients and lead to suboptimal EPO doses and inadequate treatments, which can be particularly dangerous in patients with advanced CKD." (PMID 40126283, 2025).